IL7R (interleukin 7 receptor)
Diseases named in the same sentence as IL7R in open-access papers (continued):
Sharing a sentence is not in itself a finding about the gene and the disease.
melanoma (continued). "Collectively, our findings underscored the core position of IL‐2RA, IL‐2RG, IFNG, IL‐7R, and JAK—STAT pathway in melanoma metastasis." (PMID 34159752, 2021). "Elevated IL2RA, IL2RG, IL7R, and IFNG expression may play a central role in promoting melanoma metastasis through up regulation of intratumoral regulatory T—cell proportion mainly by activation of JAK—STAT signaling pathway." (PMID 34159752, 2021). "Elevated IL2RA, IL2RG, IL7R, and IFNG expression may play a central role in promoting melanoma metastasis via increase in intratumoral regulatory T cell proportion, mainly by activation of the JAK–STAT signaling pathway." (PMID 34159752, 2021). "In addition, expression of IL-7R and/or the IL-7R pathway is significantly greater in immune checkpoint inhibitors (ICI) responders versus non-responders in melanoma, NSCLC, ovarian, TNBC, HNSCC, and/or kidney malignancies." (PMID 39281684, 2024). "To investigate whether the distinction also exists between normal and melanoma tissue, we tested the tetrad of IL2RA, IL2R, IFNG, and IL7R transcriptional expression between normal samples and melanoma samples with RT‐PCR, and observe the same expression pattern as expected." (PMID 34159752, 2021). "This tumor-specific population has a distinct epigenome, superior antitumor function, and can be enriched for adoptive cell therapy based on high IL-7R expression, without knowledge of tumor antigens, and may thus help improve melanoma therapy in the postsurgical or postimmunotherapy setting." (PMID 37459511, 2023).
Arthritis (19 papers, 2012 to 2025). Inflammation of a joint. "IL-7 receptor (gene il7r), as a pro-inflammatory-acting receptor, is associated with arthritis for immunocompetent cells both of adaptive and innate immune system." (PMID 32308655, 2020). "The strongest association observed was with a self-reported maternal family history of arthritis suggesting a genetic link, although recent data provided contradictory evidence with respect to associations between IL-7R polymorphisms and RA." (PMID 25533722, 2014). "In line with this, we demonstrated that local levels of MPO were abundantly present and strongly reduced with IL-7R blockade, indicating that IL-7R-induced T-cell activation and increased arthritis are associated with increased granulocyte activity in the inflamed joints." (PMID 22676399, 2012). "IL-7-driven arthritis is characterized by an increase in IL-7R+ macrophages, which contribute to disease severity by promoting the differentiation of inflammatory M1 macrophages and bone-eroding osteoclasts." (PMID 40313966, 2025). "Anti-TNF therapy, which reduces IL-7R expression in macrophages, has been shown to ameliorate IL-7-induced arthritis, further underscoring the role of IL-7R in inflammatory diseases." (PMID 40313966, 2025). "Blocking IL-7 or IL-7R has been shown to reduce inflammation and bone erosion in animal models of arthritis." (PMID 40313966, 2025). "Consistently, blocking IL-7 or IL-7R function can attenuate collagen-induced arthritis monocyte recruitment and osteoclast differentiation." (PMID 36311761, 2022). "Injections with IL-7 in a collagen-induced arthritis (CIA) model induced increased arthritis severity while administering a monoclonal anti-IL-7R antibody in the same model reduced disease severity." (PMID 26110994, 2015). "In-line with the observed clinical arthritis scores, the anti-IL-7R treated TSLPR-/- mice showed an even lower radiological score (0.1 ± 0.1; p<0.001), which was significantly lower than the scores in all three other groups." (PMID 26110994, 2015). "In the anti-IL-7R treated TSLPR-/- mice, strongly ameliorated clinical arthritis and immunopathology were associated with decreased levels of IL-17-associated cytokines IL-17 and IL-1β locally and IL-6 systemically." (PMID 26110994, 2015). "Supporting these findings, IL-7R blockade was associated with reduced IFN-γ and IL-17 levels and with reduced arthritis severity and immunopathology." (PMID 22676399, 2012). "Apart from the expression of IL-7 and IL-7R, the immunostimulatory capacities of IL-7 suggest an important contribution of IL-7 in joint inflammation in RA." (PMID 22676399, 2012). "Likewise, but at transcriptome level, in autoantibody-positive arthralgia patients, risk factors for progression to arthritis were reported to be involved in cytokine- and chemokine-mediated immunity, including low levels of IFNG and IL-7R." (PMID 33168080, 2020). "Moreover, IL-7R and IGF-1 remained significantly associated even after correction for known predictors (ACPA, CRP, imaging-detected subclinical joint inflammation; p = 0.039, p = 0.005, respectively)." (PMID 33168080, 2020). "These IL-7R+ B cells seemed to have a proinflammatory role in arthritis, suggesting that the IL-7/IL-7R system might be a potential drug target." (PMID 33168080, 2020). "It was shown, that IL-7 stimulated IL-7R+ mature B cells act pro-inflammatory (increased clinical score, increased anticollagen type II antibodies) after cell transfer in collagen type II-induced arthritis in DBA/1 mice." (PMID 32308655, 2020). "In addition, IL-7R blockade prevents collagen-induced arthritis." (PMID 22676399, 2012). "Together, this indicates that blockade of IL-7 or the IL-7R, preventing IL-7R-induced immune activation by IL-7, might be successful therapeutic strategies to inhibit T-cell-driven inflammation and joint destruction in arthritis." (PMID 22676399, 2012).
Arthritis (continued). "We evaluated the effect of inhibition of IL-7R- and TSLPR-signalling as well as simultaneous inhibition of IL-7R- and TSLPR-signalling in murine experimental arthritis." (PMID 26110994, 2015). "Here we show that combined ablation of IL-7R and TSLPR signalling strongly inhibits experimental arthritis and almost completely prevents immunopathology." (PMID 26110994, 2015). "Treatment of WT mice with anti-IL-7R (25 ± 5.9, p = 0.008; Mean area under curve ± SEM) or TSLPR-/- mice treated with PBS (24.1 ± 6.0, p = 0.019) significantly reduced clinical arthritis score compared to PBS treated WT mice (50.7 ± 6.8)." (PMID 26110994, 2015). "Arthritis severity and immunopathology were decreased in WT mice treated with anti-IL-7R, in TSLPR-/- mice, and the most robustly in TSLPR-/- mice treated with anti-IL-7R." (PMID 26110994, 2015). "However, only a few IL-7R-positive cells were observed in mice treated with A7R-ADC-MMAE, demonstrating that A7R-ADC effectively counteracted both steroid-sensitive and steroid-resistant cell types in this model of arthritis." (PMID 28878234, 2017).
colitis (18 papers, 2012 to 2025). Inflammation of the colon. "In addition, our colitis models provided the opportunity to assess the cell types and functions affected by blocking IL-7Rα in mice where intestinal immunopathology is associated with T cells (in Mdr1a−/− mice), and innate immune cells (in Rag2−/− mice)." (PMID 23057802, 2012). "In TCRα−/− mice and T-cell-transfer-induced colitis, high expression of IL-7Rα on T cells is associated with colitis, and IL-7-producing bone marrow cells may harbor colitogenic memory CD4+ T cells." (PMID 23057802, 2012). "IL-7Rα antagonists have been shown to inhibit innate and adaptive inflammatory responses in different experimental models of colitis." (PMID 40240976, 2025). "Another study showed that toxin-conjugated anti-IL-7R Ab treatment completely ameliorated established, ongoing colitis in the mouse model." (PMID 40323267, 2025). "miR-31 reduces the inflammatory response in DSS- and TNBS-induced mice colitis by repressing expression of inflammatory cytokine receptors IL7R and IL17RA." (PMID 35967345, 2022). "Prompted by this finding, we assessed the functional contribution of these T cells and found that indeed combined blockade of IL-7R/IL-7 interaction and GM-CSF proved to be very effective in harnessing GvHD driven colonic inflammation." (PMID 29910804, 2018). "Two other groups found that the IL-7/IL-7R-dependent signaling pathway is involved in both the immune response in the intestinal mucosa and in the development of colitis." (PMID 29854799, 2018). "In Rag2−/− mice where colitis was triggered by Hb-infection, treatment with an anti-IL-7R antibody controlled innate inflammatory responses by reducing macrophage and dendritic cell numbers and their activity." (PMID 23057802, 2012). "Given the significant alterations of chemokines and cytokines associated with innate immune cells in the serum and colon in the Mdr1a−/− model, we explored anti-IL-7Rα treatment in a Rag2−/− model of colitis." (PMID 23057802, 2012). "In mice, overexpression of IL-7 results in chronic colitis, and T-cell adoptive transfer studies suggest that memory T cells expressing high amounts of IL-7R drive colitis and are maintained and expanded with IL-7." (PMID 23057802, 2012). "Similar to the situation in Il2rg−/− mice, which are unable to signal through IL-7R, specific IL-7R blockade significantly diminished colonic ILCs and suppressed colitis." (PMID 23063332, 2012). "Our findings demonstrate an important function of IL-7R-driven immunity in experimental colitis and indicate that the therapeutic efficacy of IL-7R blockade involves affecting both adaptive and innate immunity." (PMID 23057802, 2012). "We used two mouse models of bacterial-induced colitis to study the effects of blocking IL-7Rα on IBD: a T- and B-cell-sufficient strain (Mdr1a−/−) and a T- and B-cell-deficient strain (Rag2−/−)." (PMID 23057802, 2012). "Our studies demonstrate an important function of IL-7R-driven immunity in experimental colitis and indicate that the therapeutic efficacy of IL-7Rα blockade involves affecting both adaptive and innate immunity." (PMID 23057802, 2012). "The importance of IL-7R signaling in TRUC disease was highlighted by the dramatic reduction in intestinal ILCs and attenuated colitis following IL-7R blockade." (PMID 23063332, 2012). "Mdr1a−/− mice were chosen to test the effects of anti-IL-7Rα in colitis because they are a T- and B-cell sufficient strain." (PMID 23057802, 2012). "Treatment of mice with an anti-IL-7R antibody was effective in reducing colitis in Hb-infected Mdr1a−/− mice by reducing T-cell numbers as well as T-cell function." (PMID 23057802, 2012). "Our results show that IL-7Rα blockade can ameliorate bacterial-induced colitis, and that this effect involves not only T cells but also innate immune cells such as macrophages, DC, and NK cells." (PMID 23057802, 2012).
colitis (continued). "Our findings demonstrate an important function of IL-7R-driven immunity in experimental colitis involving both adaptive and innate immunity." (PMID 23057802, 2012). "To determine the effectiveness of blocking IL-7Rα in colitis, we administered an anti-IL-7Rα antibody to Mdr1a−/− mice beginning one week prior to infection with Hb and continuing for the duration of the experiment." (PMID 23057802, 2012). "In Hb-infected Mdr1a−/− mice, the lower dose of anti-IL-7Rα M595 (50 μg) was as effective in preventing colitis as the higher dose (500 μg), despite the lower dose having less of an effect on reducing T-cell numbers (in MLN)." (PMID 23057802, 2012). "In Hb-infected Rag2−/− mice, we found that both pDCs and mDCs were significantly increased with colitis and dramatically decreased with anti-IL-7Rα treatment, especially IL-7Rα+ pDCs." (PMID 23057802, 2012). "We examined the contribution of IL-7R on inflammation and disease development in two models of experimental colitis: Helicobacter bilis (Hb)-induced colitis in immune-sufficient Mdr1a−/− mice and in T- and B-cell-deficient Rag2−/− mice." (PMID 23057802, 2012). "Selective elimination of IL-7R-expressing T cells ameliorated established, ongoing colitis." (PMID 35324681, 2022). "Successful treatment of colitis with an anti-IL-7Rα antibody was associated with decreases in T-cell and non-T-cell populations, as well as a reduction of inflammatory cytokines and chemokines." (PMID 23057802, 2012). "Taken together, these results indicate that an innate-immune signature occurred both locally and systemically in Hb-infected mice and suggested that an anti-IL-7Rα antibody could regulate adaptive- as well as innate-immune responses in colitis." (PMID 23057802, 2012). "However, the blockade of the IL-7/IL-7R signaling pathway renders T cell-deficient mice more sensitive to chemically-induced IEC damage and subsequent colitis." (PMID 22384106, 2012). "This may facilitate wound healing after DSS-induced IEC damage and may explain why Rag− mice were protected from colitis in an IL-7R-dependent fashion." (PMID 22384106, 2012). "It is possible that IL-7R expression by cells other than CD4+ T cells has a modest effect in their model as they noted a trend of increased colitis scores in IL7R−/− x Rag2−/− recipients of wildtype naïve T cells compared to Rag2−/− -only recipients, although these differences were not significant." (PMID 23057802, 2012). "Furthermore, we demonstrate that IEC accumulate in the colon of lymphopenic mice in an IL-7/IL-7R-dependent fashion correlating with decreased colitis induction." (PMID 22384106, 2012). "Thus, in line with the reduction in myeloid cells, innate-immune mediators were also reduced with IL-7Rα blockade and strongly indicate that anti-IL-7Rα treatment controls colitis by multiple mechanisms." (PMID 23057802, 2012). "Therefore, we used two doses of anti-IL-7Rα M595 to determine if a 10-fold lower dose would preserve lymphocyte numbers yet still afford protection from colitis." (PMID 23057802, 2012). "The therapeutic effect on endoscopic signs of colitis was accompanied by diminished expression levels of proinflammatory mediators within colon tissues as we detected reduced amounts of Il1b, Tnf, Csf2, and Ifng transcripts in anti-IL-7R/anti-GM-CSF- compared to control antibody-treated mice." (PMID 29910804, 2018). "Therefore, we used T- and B-cell deficient Rag2−/− mice to determine the effects of blocking IL-7Rα on non-lymphoid cells in Hb-induced colitis." (PMID 23057802, 2012). "However, the adoptive transfer model of colitis is dependent on IL-7R-mediated expansion of T cells for induction of colitis, in contrast to our models wherein bacterial antigens drive inflammation and colitis involving resident host T cells (when present) and other innate immune cells." (PMID 23057802, 2012).
colitis (continued). "Anti-IL-7Rα-treated Hb-infected mice were normal with well-formed fecal pellets in the distal colon and normal diameter of the proximal colon and were generally considered normal histologically (anti-IL-7R M595/500 Hb) or had some mild focal colitis (anti-IL-7R M595/50 Hb)." (PMID 23057802, 2012). "The use of a toxin-conjugated anti-IL-7Rα antibody (A7R34) by Yamazaki and colleagues suggests that selective elimination of IL-7Rαhigh CD4+ LPL is required to treat colitis." (PMID 23057802, 2012). "IL-22-producing ILC are important regulators of intestinal homeostasis, they are generated in an IL-7/IL-7R-dependent fashion and protect Rag− mice from DSS-induced colitis." (PMID 22384106, 2012). "Amelioration of disease with anti-IL-7Rα treatment in the Rag2−/− colitis model suggested that IL-7Rα expressing non-T cells, including macrophages, DCs, and NK cells are important in bacterial-induced disease." (PMID 23057802, 2012). "It would be interesting to perform these colitis studies with a re-engineered anti-IL-7Rα antibody that does not have the confounding variable of ADCC." (PMID 23057802, 2012). "Importantly, IEC hyperplasia and protection from colitis are blocked, if naive CD8+ T cells consume IL-7 or IL-7R signaling is inactive in IEC." (PMID 22384106, 2012). "In an adoptive T-cell-transfer model of colitis, Yamazaki and colleagues successfully treated ongoing colitis using a saporin-conjugated anti-IL-7Rα antibody, selectively eliminating lamina propria lymphocytes (LPL) with high expression of IL-7R." (PMID 23057802, 2012). "Hence, our results indicate that IL-7R expression by naïve T cells is sufficient to limit IEC proliferation/survival and aggravate DSS colitis even in the presence of ILC." (PMID 22384106, 2012). "The studies presented here were undertaken to better understand the contribution of IL-7R in inflammatory bowel disease in which colitis was induced with a bacterial trigger rather than with adoptive transfer." (PMID 23057802, 2012). "However, our results differ from some reports in that we demonstrate that IL-7R-mediated activity on non-T and non-B cells also contributes to experimental colitis." (PMID 23057802, 2012). "Given our results successfully treating Hb-induced colitis in Mdr1a−/− mice by inhibiting IL-7R signaling, we determined whether non-lymphoid cells also respond to anti-IL-7Rα treatment as was suggested in the mRNA and protein analysis." (PMID 23057802, 2012). "However, we further show using a bacterial trigger of colitis in a T-cell competent model and a non-T non-B cell model, that blocking IL-7Rα can decrease inflammatory responses via its effect on multiple immune cells that include not only T cells, but also B cells, macrophages, DC, and NK cells." (PMID 23057802, 2012). "Our findings differ from the conclusions reported by Shinohara and colleagues in which they used an adoptive transfer model of colitis to show that expression of IL-7Rα on CD4+ T cells, but not on other cells (NK cells, granulocytes, macrophages, and DC), was essential for development of colitis." (PMID 23057802, 2012).